CBS (cystathionine beta-synthase)
Diseases named in the same sentence as CBS in open-access papers (continued):
Sharing a sentence is not in itself a finding about the gene and the disease.
cancer (continued). "Perhaps of greatest interest is understanding how this study adds to the growing body of literature that implicates the TSS pathway and its functional enzymes (i.e., CTH and CBS) as well as the metabolites utilized and produced by this pathway in GBM and in the broader field of cancer biology." (PMID 38299594, 2024). "Cystathionine β-synthase (CBS), CSE (cystathionine γ-lyase) and 3-mercaptopyruvate sulfurtransferase (3-MST) have emerged as three significant sources of hydrogen sulfide (H2S) in various forms of mammalian cancer." (PMID 36978895, 2023). "Likewise, the pharmacological inhibition of CBS and 3‐MST blocks electron transport and mitochondrial energy production in various cancer cells, whereas replenishment of substrates for these enzymes reversed this process." (PMID 36929586, 2023). "In other words, CBS, CSE, and 3-MST may serve as new molecular markers and biomarkers for the diagnosis and treatment of cancer." (PMID 35684331, 2022). "In various cancer cells, endogenously produced H2S—from different enzymatic sources: CBS, CSE and/or 3-MST, depending on the cancer type —has been shown to contribute to the maintenance of cancer cell growth, invasiveness, anticancer drug resistance, and tumor angiogenesis." (PMID 32183148, 2020). "Furthermore, increased expression of CBS and CSE was documented in different cancer types, such as colorectal, ovarian, breast, prostate and melanoma, and was shown to contribute to cancer progression, energy metabolism and drug resistance." (PMID 31382676, 2019). "In cancer cells, enzymes involved in H2S synthesis, such as CBS, CSE and MST were found to be overexpressed, and growing evidence suggests that H2S and related reactive sulfide species, including sulfane sulfur species, play a role in cancer biology." (PMID 31382676, 2019). "The functional role of changes in the levels of CBS in other types of cancer has not been explored yet5 To our knowledge studies in lung have not been reported." (PMID 27924828, 2016). "In this regard, CBS represents an attractive target with minimal to no expression in OSE cells but with enhanced expression in cancer cells." (PMID 24236104, 2013). "S-adenosyl-L-methionine (SAM), a metabolic activator at low to moderate levels of CBS, produces H2S as an endogenous pro-growth and bioenergetic factor in early stages of colon carcinogenesis, but high doses of SAM downregulate CBS expression and inhibit cancer cell bioenergetics and proliferation." (PMID 38448410, 2024). "Indeed, enhanced expression of CBS and CSE enzymes in human cancer cells has been widely reported." (PMID 37509058, 2023). "Cancer cells may increase the uptake of Se through system Xc− or as SELENOP through LRP8 receptor to protect the cell from ferroptotic cell death, while also modulating key enzymes of the trans-selenation pathway, such as CBS, CGL, or SCLY." (PMID 36358931, 2022). "Aside from the hijacking of the xCT transporter to promote intake of Se and Sec instead of cysteine in certain cancer cells, there are enzymes involved in the metabolism of Se, such as CGL, CBS, and SCLY, that may have roles in cancer cell survival and/or proliferation." (PMID 36358931, 2022). "CBS and 3-MST expression may be regulated both at the level of transcription, as well as at the level of degradation/protein stability; the importance of these mechanisms in various cancers remain to be further defined." (PMID 33499368, 2021). "Likewise, AOAA, a pharmacological inhibitor of CBS, or HMPSNE, a pharmacological inhibitor of 3-MST, suppresses electron transport and mitochondrial bioenergetics in various cancer cell types, while supplementation of these enzymes’ respective substrates further stimulates these processes." (PMID 33499368, 2021).
cancer (continued). "Furthermore, the inhibition of CBS leads to anti-tumor activity especially in breast cancer, ovarian cancer, and colon cancer, while the effect of CSE or 3-MST inhibition has been largely unexplored in cancer cells." (PMID 34944543, 2021). "Therefore, CBS could potentially affect a number of cellular processes, which in turn impact EMT and related drug resistance, and eventually cancer growth and progression." (PMID 32770044, 2020). "However, this cell line does not express the AR, and the low levels of CBS did not seem to correlate with the cancer phenotype." (PMID 27472325, 2016). "Although clinical trials investigating H2S donor for cancer therapy have not yet been conducted, given the context-dependent role of CBS/H2S in tumor development, the therapeutic potential of H2S supplement in a subgroup of patients with high levels of CBS expression merits additional study." (PMID 35172821, 2022). "Since CT26 cells do not express CBS (another H2S-producing enzyme that contributes to the maintenance of various biological effects in various other forms of cancer), this cell line may serve as a useful tool to investigate the functional role of 3-MST in cancer cells in vitro and in vivo." (PMID 32183148, 2020). "Finally, following the identification of cancer-related proteins CTTN, CSTB and CBS as novel proteomic targets of deoxyelephantopin, it is also tempting to speculate about potential biomedical application of synthetic analogues of this intriguing natural product as novel anticancer therapeutics." (PMID 27539788, 2016). "Recent studies have indicated a negative correlation between the transcription levels of CBS and SLC7A11 (xCT) in cancer cell lines from the Cancer Cell Line Encyclopedia31 across various cancer types." (PMID 37381723, 2023). "CBS up-regulation in tumor cells sometimes occurs in combination with up-regulation of other H2S-producing enzymes (CSE, 3-MST); in other forms of cancer it is not CBS but one or more of the other H2S-producing enzymes that becomes up-regulated." (PMID 32365821, 2020). "Unlike CGL and CBS, the role of SCLY in cancer is poorly understood." (PMID 36358931, 2022). "Furthermore, if the role of CBS and CSE in cancer is related to cysteine anabolism or catabolism is not always clear." (PMID 32714858, 2020).
tumor (106 papers, 2005 to 2025). "The higher H2S levels are induced by elevated CBS expression and are also associated with the proliferation of multiple tumor types such as colon, ovarian, breast, and prostate cancer." (PMID 34439295, 2021). "Moderate to strong CBS immunoreactivity was associated with a serous histology and a higher tumor grade, although significant expression was also seen in early-stage tumors." (PMID 35366284, 2021). "It is relevant to point out that prior cancer studies have reported both loss and overexpression of the CBS gene, relating to tumor suppressive and oncogenic properties respectively, with the latter associated with an abnormal bioenergetic phenotype." (PMID 34074348, 2021). "We show that loss of CBS activity in vitro recapitulates a subset of methylation in GC CIMP tumors, and that besides GC, epimutations at CBS are also associated with CIMP in other tumor types, implying a broader role in cancer." (PMID 34074348, 2021). "Cystathionine beta synthase is generally associated with drug resistance, including resistance to anti-tumor agents." (PMID 30174791, 2018). "The deregulation of CBS and its association with a malignant tumor phenotype is potentially associated to the crucial role of CBS in methionine metabolism and the maintenance of intracellular redox homeostasis." (PMID 23152928, 2012). "CBS deficiency promoted Treg-mediated immune evasion and tumor growth in mice, suggesting that the CBS/H2S axis may control immune evasion in the TME." (PMID 36588686, 2022). "Notably, pan-cancer analysis indicated that these associations were observed in other tumor types beyond GC, implying a broader role for CBS epimutation in shaping tumor biology." (PMID 34074348, 2021). "Utilizing this pharmacological probe, we demonstrated that the selective inhibition of CBS could suppress cell proliferation, cause cell cycle arrest at S phase and significantly reduce in vivo tumor growth in tumor xenograft mice model." (PMID 30258181, 2018). "The overexpression of CBS was reported to significantly enhance cell apoptosis in vitro and suppress tumor growth in vivo." (PMID 40860678, 2025). "In clinical NB cases, higher OGT, FOXC1, ASNS, GPT2, CBS, or FTH1 levels are correlated with worse survival, while lower ecircOGT or OGT-570aa expression is associated with tumor progression." (PMID 40416363, 2025). "Studies have shown that the elevated activity of CBS plays a significant role in promoting tumor growth, invasiveness, and metastatic potential." (PMID 38828455, 2024). "Inhibiting tumor growth was achieved through CBS gene knockout and the application of aminooxyacetic acid (AOAA), a broad inhibitor of PLP-dependent enzymes, on CML-derived K562 cells, which led to the activation of the apoptosis pathway." (PMID 39062461, 2024). "Using an inhibitor of GCLC, buthionine sulfoximine (BSO), we found that BSO treatment significantly decreased intracellular GSH level, increased Erastin-induced cell death and inhibited proliferation in tumor cells co-cultured with CBS-disrupted CAFs." (PMID 38389839, 2024). "Combination of HSF1 and CBS knockout decreases tumor size for a small cell PCa xenograft mouse model." (PMID 38172561, 2024). "We next investigated the proliferative capacity and lipid peroxidation of the tumors using Ki-67 and 4-HNE staining, which confirmed that the cysteine-containing diet reversed the effects of stromal CBS depletion on tumor proliferation and lipid peroxidation." (PMID 38389839, 2024). "This was due to the overexpression of cystathionine β synthase (CBS) in tumor cells, which produced more H2S than in normal cells." (PMID 39090112, 2024). "Elevated GSH levels were observed in co-cultured PDAC cells after NAC treatment while NAC treatment counteracted the increased cell death and decreased proliferation seen in tumor cells co-cultured with CBS-disrupted CAFs." (PMID 38389839, 2024).
tumor (continued). "Meanwhile, knockdown of CBS also significantly inhibites the growth of nude mouse tumor xenografts and enhances the inhibition of cisplatin." (PMID 38448410, 2024). "In the in vivo models, the silencing of CBS led to a significant decrease in tumor weight and the number of tumor nodules, while the inhibition of peritumor angiogenesis was confirmed to cause a marked reduction in CD31 staining." (PMID 38250807, 2024). "The overexpressed cystathionine b-synthase (CBS) inside tumor cells enables the decomposition of L-cysteine into hydrogen sulfide (H2S), inducing motion for nanorobots in the tumor microenvironment." (PMID 38607129, 2024). "Conversely, mitochondrial homeostasis in CRC cells was detected disrupted upon knockdown of CBS contributing to tumor energy starvation and impairing growth." (PMID 38490069, 2024). "Targeting CBS decreases PCa growth and induces tumor cell death while benign prostate cells are largely unaffected." (PMID 38172561, 2024). "This suggests that antitumor T cells with increased H2S signaling exhibit better persistence in vivo and CAR-T cells engineered to express CBS can potentiate tumor control." (PMID 39546607, 2024). "In this study, we evaluated the therapeutic potential of benserazide, a targeting CBS inhibitor, in combination with paclitaxel to inhibit tumor growth and understand the mechanism of action of these drugs." (PMID 38828455, 2024). "The elevated activity of Cystathionine beta-synthase (CBS), an enzyme responsible for producing endogenous hydrogen sulfide (H2S), plays a significant role in promoting tumor growth, invasiveness, and metastatic potential." (PMID 38828455, 2024). "LINC00336 acts as a sponge for microRNA6852, thus increasing CBS mRNA levels, and consequently stimulating tumor proliferation and inhibition of ferroptosis in NSCLC57." (PMID 37381723, 2023). "CSE abolishes the tumour suppressor effect due to CBS knockdown to a certain extent, indicating that simultaneous targeting of CBS and CSE can produce a more obvious inhibitory effect on BLBC." (PMID 36929586, 2023). "As SAM is an allosteric activator of CBS that binds to the regulatory domain of CBS and regulates H2S production, indeed, it helps in the growth of tumor cells." (PMID 37627515, 2023). "NO regulates the growth of various tumours and has a positive feedback loop with H2S.115Knockdown of CBS and CSE mitigates the production of NO, while the addition of NO donors attenuates the antitumor effect of CBS and CSE knockdown." (PMID 36929586, 2023). "S‐sulfhydration of MEK1 by H2S at Cys341 promotes phosphorylation and nuclear translocation of MEK1, thereby activating PARP‐1‐mediated DNA damage repair, which is most likely a key driver of tumour growth due to CBS or CSE overexpression." (PMID 36929586, 2023). "Using either CBS knockdown or the cystathionase (CTH) inhibitor propargylglycine (PAG) to block the TSS pathway significantly increases ferroptosis in tumor cells." (PMID 38274225, 2023). "The protein level of CBS in the tumor was further detected, the data indicated that the CBS level in CBS group was higher than that in Mock group, and the expression level of CBS in sh-CBS group was lower than that in sh-Scb group." (PMID 35795862, 2022). "In tumor cells with high CBS expression, silencing or inhibition of CBS can obtain “mirror” biological responses, such as the inhibition of cell proliferation, invasion, and cell bioenergetics." (PMID 36558139, 2022). "CBS mechanisms must be characterized to determine their specific roles in tumor cell proliferation, invasion, and metastasis." (PMID 35684331, 2022). "The requirement of CBS for the maintenance of AIS implicates it as a putative tumor suppressor during PI3K/AKT pathway-driven tumorigenesis." (PMID 35758651, 2022). "Next, we assessed the effect of CBS overexpression on tumor metastasis by intrasplenic injection of HT-29 cells into nude mice (n = 6 for each group)." (PMID 35172821, 2022).
tumor (continued). "According to the current research results, CBS-derived H2S is identified as the target of tumor growth factor and anticancer drugs." (PMID 36558139, 2022). "(D) The percentage of cytosolic CBS-positive cells and (E) the intensity of cytoplasmic CBS in the tumor or adjacent normal tissues from 62 patients were shown." (PMID 35758651, 2022). "A combination of the pharmacological inhibition of CBS with AOAA and CBS silencing significantly reduced the formation of tumor xenografts." (PMID 35684331, 2022). "The results indicated that CBS overexpression inhibited tumor growth rate and the difference was significant on day 31 and 34 (*p < 0.05)." (PMID 35172821, 2022). "Analysis of NSCLC biopsies and adjacent non-tumor tissues showed selectively high levels of endogenous H2S-producing enzymes, namely CBS, CSE, and 3-MST." (PMID 36558139, 2022). "Paired with the anti-tumoral effects of cannabinoids these observations make CBs a potential substance class for targeting tumor cells and interfering with the tumor-stroma-cell cross talk." (PMID 35011711, 2022). "RNA-seq also showed that CBS, a potential tumor growth promoter, was one of the top upregulated genes." (PMID 34603448, 2021). "While CBS showed similar expression in all tumor types, we found that CSE was upregulated in IDH1m cells both at the protein and mRNA level." (PMID 34250481, 2021). "Our RNA-seq results suggested that miR-559 was one of the top downregulated miRNAs after DiAcSpm treatment, where it functioned as a tumor-suppressive miRNA by targeting CBS in CRC cells." (PMID 34603448, 2021). "The mice receiving the CBS siRNA had a 40% lower tumor weight, a 70% reduction in tumor nodules, and lower proliferation and blood vessel formation, as measured by Ki-67 and CD31 immunostaining, respectively." (PMID 35366284, 2021). "Additional studies to investigate the interaction between HNF4α and CBS will therefore help to better understand the complex role of CBS in tumor biology." (PMID 32770044, 2020). "Based on the fact that the upregulation of hydrogen sulfide (H2S)‐generating enzyme of cystathionine‐β‐synthase (CBS) in colon cancer, the H2S concentration in tumor reaches around 0.3 to 3.4 mmol L−1." (PMID 33173728, 2020). "This outcome is also justified as consumption of FO induces an upregulation of xCT and CTH proteins and reduces the expression of CBS proteins in tumor tissues." (PMID 33137095, 2020). "As expected, the silencing of CBS, on its own, slowed down the baseline proliferation rate of the tumor cells." (PMID 32365821, 2020). "Due to its rapid response, Si@BODPA was then employed for the real‐time monitoring of endogenous H2S generation in HCT116 tumor‐bearing mouse to verify elevated level of H2S due to CBS upregulation." (PMID 31763153, 2019). "In this study, we report that the inhibition of CBS caused by CH004 increases the lipid ROS, an indicator for ferroptosis, along with decreasing the viability of tumor cells." (PMID 30258181, 2018). "The antiproliferative effect observed by silencing or inhibiting CBS was recapitulated in the xenograft mouse models and patient-derived tumor xenografts." (PMID 30050925, 2018). "CBS-driven endogenous H2S production has been reported to support tumor growth by (i) maintaining mitochondrial respiration and ATP synthesis, (ii) stimulating cell proliferation and survival, (iii) redox balance, and (iv) vasodilation." (PMID 30050925, 2018). "Reduced CBS expression was significantly correlated with the poor clinic pathological parameters including tumor stage, Edmondson grade, alpha-fetoprotein (AFP) level, and overall survival." (PMID 30050925, 2018). "Consistently, CBS knockdown decreased tumor latency in U87-MG xenografts and increased tumor volume in an orthotopic model." (PMID 30050925, 2018). "Further supporting the tumor-suppressive role for CBS, exogenous H2S induced autophagy and apoptosis in HCC cells through the PI3K/Akt/mTOR pathway." (PMID 30050925, 2018).